PABPC5 (poly(A) binding protein cytoplasmic 5)
Description:
Binds the poly(A) tail of mRNA. May be involved in cytoplasmic regulatory processes of mRNA metabolism. Can probably bind to cytoplasmic RNA sequences other than poly(A) in vivo (By similarity).
Synonyms: PABP5
Tractability: PROTAC: ubiquitination databases record sites on it.
Gene: Protein-coding gene on chromosome X (91,434,595 to 91,438,584, forward strand). Ensembl gene ENSG00000174740.
Subcellular location: Cytoplasm; Mitochondrion matrix (Isoform 2)
Gene Ontology:
Molecular function: protein binding; mRNA 3'-UTR binding; poly(U) RNA binding; nucleic acid binding; RNA binding
Cellular component: cytoplasmic stress granule; cytosol; nucleus; ribonucleoprotein complex; cytoplasm; mitochondrial matrix
Homologues: Orthologues: chimpanzee PABPC5 (100% identical), rabbit PABPC5 (98% identical), dog PABPC5 (97% identical), pig PABPC5 (97% identical), mouse Pabpc5 (95% identical), rat Pabpc5 (95% identical), guinea pig PABPC5 (94% identical). Paralogues in human: PABPC4 (64% identical), PABPC1 (63% identical), PABPC3 (60% identical), PABPC4L (59% identical), PABPC1L (57% identical), PABPC1L2A (30% identical), PABPC1L2B (30% identical), RBMS1 (18% identical), RBMS3 (18% identical), RBMS2 (17% identical), HNRNPR (16% identical), SYNCRIP (16% identical), and 12 more.
Diseases named in the same sentence as PABPC5 in open-access papers:
PABPC5 is named in the same sentence as 8 diseases in open-access papers, as found by Europe PMC text mining. Sharing a sentence is not in itself a finding about the gene and the disease. The quoted sentences say what the papers report.
glioma (3 papers, 2021 to 2025). A benign or malignant brain and spinal cord tumor that arises from glial cells (astrocytes, oligodendrocytes, ependymal cells). "It has been reported that PABPC5, a protein involved in mRNA stability, binds to HCG15, increasing its levels within glioma cells." (PMID 40277941, 2025). "Finally, another important lncRNA in glioma development is HCG15, which participates in the PABPC5/HCG15/ZNF331 feedback loop regulating VM by influencing key protein expression." (PMID 40277941, 2025). "In addition, in the regulation of glioma formation, the PABPC5/HCG15/ZNF331 feedback loop involving HCG15 exerted a significant function, giving a novel target for glioma therapy." (PMID 36189204, 2022). "Similarly, in glioma, SMD is enhanced due to the upregulation of the lncRNA HCG15 that is stabilizes by the binding of PABPC5." (PMID 35008641, 2021).
premature ovarian failure (3 papers, 2014 to 2024). "An involvement in mitochondrial metabolism and apoptosis is described, and an association between premature ovarian failure in ovarian diseases as well as ovarian cancer is linked to PABPC5 in humans." (PMID 39300329, 2024). "In addition, methylation-dependent silencing of P4HA3 in B-cell lymphoma cell lines was previously shown to be reversible by DNMTI treatment, and PABPC5 has been associated with premature ovarian failure but a role for either gene in OC has not been previously reported." (PMID 25003579, 2014).
viral infection (1 paper, 2015). "PABPC5, which maps to a focal deletion on Xq, is suppressed upon viral infection." (PMID 25875127, 2015).
tumour (1 paper, 2023). "Substantial CNV deletions were observed in PABPC5, MSH6, IFI16, GNS, ERCC4, BRCA1 and ACACB, while substantial CNV amplification was observed in most tumour types for the remaining genes." (PMID 37660060, 2023).
PABPC5 also shares sentences with these, for which no sentence is quoted: B-cell lymphoma (1 paper); cancer (1); ovarian carcinoma (1); ovarian diseases (1).